ZEB2 (zinc finger E-box binding homeobox 2)
Diseases named in the same sentence as ZEB2 in open-access papers (continued):
Sharing a sentence is not in itself a finding about the gene and the disease.
Mowat-Wilson syndrome (continued). "As a transcription factor, ZEB2 is widely known to be involved in tumor progression and aggressiveness, embryogenesis development, and Mowat Wilson syndrome (MWS) phenotypes." (PMID 26895378, 2016). "ZEB2 has been involved in Mowat-Wilson syndrome (MWS), a multiple congenital anomaly syndrome characterized by a distinct facial phenotype." (PMID 24750690, 2014). "Targeted gene testing, such as testing for the ZEB2 gene affected in Mowat-Wilson syndrome, maybe a reasonable next step as well." (PMID 35844343, 2022). "For example, two carrier children in family GL_005 inherited an intronic variant within ZEB2 from their noncarrier parent, whose altered dosage is associated with Mowat-Wilson syndrome." (PMID 34657631, 2021). "Interestingly, patients with Mowat-Wilson syndrome also exhibit ventriculomegaly, or enlarged ventricles, a phenotype paralleled by the enlarged neuroepithelial buds seen in ZEB2+/− organoids." (PMID 33765444, 2021). "Interestingly, the symptoms of PMS in cattle were similar to Mowat-Wilson syndrome (MWS) in humans, which is also associated with genetic variations in the human ZEB2 gene." (PMID 33046754, 2020). "Mutations in KMT2D (MIM 147920), NF1 (MIM 162200), and ZEB2 (MIM 235730) are known to cause human monogenic Mendelian syndromes (Kabuki syndrome, neurofibromatosis type 1, and Mowat-Wilson syndrome, respectively), and cardiac malformations in these syndromes occur in 3–50% of patients." (PMID 29089047, 2017). "In addition, a milder presentation of Mowat-Wilson syndrome was considered in one subject (No. 71) and confirmed by the detection of a de novo frameshift variant in exon 10 of ZEB2 (zinc finger E-box binding homeobox 2) (Suppl.P&M)." (PMID 40735694, 2025). "Mowat-Wilson syndrome (MOWS; OMIM #235730) is a rare neurodevelopmental disorder (NDD) caused by heterozygous deletions or loss-of-function (LoF) variants of the ZEB2 gene (HGNC:14881; locus 2q22.3)." (PMID 38351292, 2024). "Mice lacking Zeb2 are embryonic lethal, while patients with heterozygous abnormalities in Zeb2 often develop Hirschsprung’s disease and Mowat-Wilson syndrome." (PMID 30076102, 2018). "While some large deletions extend in the chromosomal region 2q22.3, these deletions do not include the zinc finger E box-binding homeobox 2 gene (ZEB2, MIM 605802), the causative gene for Mowat-Wilson syndrome (MIM 235730)." (PMID 25853262, 2015).
gastric cancer (53 papers, 2014 to 2025). A primary or metastatic malignant neoplasm involving the stomach. "MiR-506 levels and ZEB2 levels were inversely correlated in gastric carcinoma, and low miR-506 levels in gastric carcinoma were associated with poor prognosis." (PMID 30923258, 2019). "The present study validated the prognostic value and clinicopathological association of ZEB1 and ZEB2 in digestive cancers, especially in gastric cancer." (PMID 28416756, 2017). "This newly identified miR-506/ZEB2 axis might be a promising diagnostic biomarker for gastric carcinoma patients and could be a potential therapeutic target in the management of gastric carcinoma." (PMID 30923258, 2019). "suggesting presence of a causal link between miR-506 and ZEB2 in gastric carcinoma." (PMID 30923258, 2019). "In future studies, it may be interesting to study the miR-506 targeting of ZEB2 downstream signaling pathways, and the molecular mechanisms underlying the downregulation of miR-506 in gastric carcinoma." (PMID 30923258, 2019). "Besides, high ZEB2 expression was strongly associated with lactate dehydrogenase A (LDHA) expression in gastric cancer, and LDHA was a crucial enzyme in the final step of the Warburg effect, through which high rate of glycolysis was executed in cancer cells." (PMID 28416756, 2017). "For instance, our previous study showed that circTNIK promoted gastric cancer progression through sponging of miR-138-5p to influence the level of ZEB2." (PMID 38510750, 2024). "For example, lncRNA-CTS can up-regulate ZEB2 expression by adsorbing miR-505 to facilitate CC cell migration, invasion and EMT; lncRNA UCA1 can regulate the miR-203/ZEB2 axis to facilitate gastric cancer cell migration and invasion." (PMID 35435130, 2022). "miR-145 also regulates the invasion of gastric cancer by targeting ZEB2 and N-cadherin to regulate epithelial-mesenchymal transition." (PMID 34631898, 2021). "ZEB2 can promote the migration and invasion of gastric cancer cells by regulating epithelial–mesenchymal transition (EMT) and is a potential target for gene therapy of invasive gastric cancer." (PMID 34368227, 2021). "Overexpression of miR-506 suppressed metastasis of gastric carcinoma cells by targeting zinc finger E-box-binding homeobox 2 (ZEB2)." (PMID 33621206, 2021). "Another member of miR-200 family, known as miR-200c, sensitizes gastric cancer cells to cisplatin and enhances chemotherapeutic efficacy by suppressing ZEB2 expression." (PMID 32664703, 2020). "In contrast, another mechanism reported for miR-203 regulation is sponging via the competing endogenous RNA (ceRNA) long non-coding RNA (lncRNA) UCA1, which resulted in an upregulated ZEB2-mediated EMT pathway in gastric carcinoma." (PMID 32708601, 2020). "In intestinal-type gastric cancer cell lines, silencing LDHa downregulates Zeb2 and the synergistic decrease of LDHa and Zeb2 decreased cancer invasion, metastasis and poor prognosis." (PMID 31849832, 2019). "With limited number of the clinical cases, we were able to evaluate correlations between miR-506 and ZEB2 expression in gastric carcinoma specimens, suggesting that this regulation is strong." (PMID 30923258, 2019). "Since our data suggest a relationship between miR-506 and ZEB2 in gastric carcinoma, and since bioinformatics analysis suggests ZEB2 as a target for miR-506, we examined this regulatory axis with a human gastric carcinoma cell line, AGS." (PMID 30923258, 2019). "To assess the relationship between miR-506 and ZEB2 in gastric carcinoma, we examined their correlation using the 26 gastric carcinoma specimens." (PMID 30923258, 2019). "In this study, analysis of TCGA and KmPlotter data also showed that high expression of ZEB2 or Sp1 is correlated with poor survival of colorectal and gastric cancer patients." (PMID 29416649, 2018).
gastric cancer (continued). "The role of ZEB family is specific to cancer: ZEB1 is important in the invasion and metastasis of colon cancer, while ZEB2 is important in pancreatic cancer, gastric cancer and ovarian cancer." (PMID 30356400, 2018). "In the present study, we have shown that IL-6 secreted by CAFs induced EMT of gastric cancer cells, which is characterized by losing epithelial markers E-cadherin and acquiring of mesenchymal markers N-cadherin and ZEB2." (PMID 28186964, 2017). "We only performed secondary analyses in gastric cancer, because only in gastric cancer did both ZEB1 and ZEB2 have significant prognostic value, and studies concerning gastric cancer provided adequate data for secondary analyses." (PMID 28416756, 2017). "Specifically, miR-338-3p inhibited the epithelial-mesenchymal transition in gastric cancer by downregulating ZEB2 and MACC1/Met/Akt signaling." (PMID 28969055, 2017). "ZEB2 was also reported to promote invasion and metastasis of gastric cancer by inhibiting E-cadherin." (PMID 27861158, 2016). "Then, we detected the expression of transcriptional factors, such as snail, twist, ZEB1 and ZEB2 in gastric cancer cells using real-time PCR." (PMID 27102302, 2016). "Overall, the results of the present study suggest that IGF-I induced EMT by the activation of a PI3K/Akt-GSK-3β-ZEB2 signaling pathway in gastric cancer BGC-823 cells." (PMID 25435948, 2015). "The expression levels of miR-141 were significantly decreased in the gastric tumor tissue samples, compared with in the non-tumor tissue samples; however, mRNA expression levels of ZEB2 were increased in the gastric cancer tissue samples." (PMID 25975736, 2015). "By using a luciferase reporter assay, it was demonstrated that ZEB2 was the target of miR-141 in gastric cancer cell lines." (PMID 25975736, 2015). "Forced overexpression of miR-141 significantly reduced the luciferase activity of the 3′-untranslated region of ZEB2 in gastric cancer cells." (PMID 25975736, 2015). "Here, we demonstrated that IGF-I initiated EMT in gastric cancer cells and increased their migration potential through up-regulation of ZEB2." (PMID 24885194, 2014). "This process was at least partially dependent on Akt/ERK downstream signaling pathways, which were upstream factors of ZEB2 activation in gastric cancer cells in vitro." (PMID 24885194, 2014). "Together, these findings demonstrate that the ubiquitin ligase Cbl-b represses IGF-I-induced EMT, likely through targeting IGF-IR for degradation and further inhibiting the Akt/ERK-miR-200c-ZEB2 axis in gastric cancer cells." (PMID 24885194, 2014). "Here, we reveal the existence of an Akt/ERK-miR-200c-ZEB2 axis in IGF-I-induced EMT in gastric cancer cells." (PMID 24885194, 2014). "Lactate was shown to promote EMT in gastric cancer cells by upregulating ZEB2." (PMID 40507273, 2025). "In addition, it was clarified that epidermal growth factor (EGF) induced the upregulation of ZEB1 and ZEB2 via the Akt signaling pathway in gastric carcinoma, which was consistent with the results of our research." (PMID 40510028, 2025). "In another study on gastric cancer, miR-506 reduced cell migration and invasion via ZEB2 sponging." (PMID 37051101, 2023). "Interrogation of CCLE database revealed that FZD5 is positively correlated with epithelial-related factors CDH1 (E-cadherin), OCLN (Occludin), EPCAM and ELF3, while negatively correlated with mesenchymal-related factors VIM (Vimentin), SNAI2 (Slug), ZEB1 and ZEB2 in 37 gastric cancer cell lines." (PMID 33618713, 2021). "In gastric cancer cells, miR-203 diminishes cancer metastasis through ZEB2 down-regulation." (PMID 32664703, 2020). "Our findings here were thus summarized in a schematic, showing that that miR-506 may function as a tumor suppressor by targeting and suppressing ZEB2 protein translation in gastric carcinoma." (PMID 30923258, 2019). "Moreover, in the gastric carcinoma samples, we detected significantly higher levels of ZEB2, compared to NGT." (PMID 30923258, 2019).
gastric cancer (continued). "The regulatory relationship between UCA1 and ZEB2 implied that the UCA1–ZEB2 axis may be an important regulatory pathway in the progression of gastric cancer." (PMID 30464170, 2018). "Furthermore, by conducting secondary analyses we confirmed both ZEB1 and ZEB2 played important roles in gastric cancer prediction." (PMID 28416756, 2017). "Overall, to the best of our knowledge, the present study is the first to report that IGF-I induces EMT, thereby upregulating ZEB2 expression, and that a potential PI3K/Akt-GSK-3β-ZEB2 signaling pathway is involved in IGF-I-induced EMT in BGC-823 gastric cancer cells." (PMID 25435948, 2015). "ZEB2 may serve as a clinical biomarker to identify patients who can benefit from IGF-IR-targeted therapy in gastric cancer." (PMID 25435948, 2015). "Furthermore, the mRNA expression levels of ZEB2 mRNA were inversely correlated with the levels of miR-141 in gastric cancer tissue." (PMID 25975736, 2015). "The results of the present study suggest that miR-141 may have an important role in the inhibition and migration of gastric cancer cells, by targeting ZEB2." (PMID 25975736, 2015). "IGF-I-induced gastric cancer cell EMT was accompanied by ZEB2 up-regulation." (PMID 24885194, 2014). "Thus, our results suggest that miR-506 may function as a tumor suppressor and targets and inhibits ZEB2 in gastric carcinoma." (PMID 30923258, 2019). "We then tested whether UCA1 promotes gastric-cancer metastasis in a miR-203/ZEB2-dependent manner." (PMID 30464170, 2018). "However, whether IGF-I can induce gastric cancer cell EMT or up-regulate expression of ZEB2, another ZEB transcription factor family member, is unknown." (PMID 24885194, 2014). "The connection between IGF-1 and ZEB2 was shown in gastric cancer cells, where IGF-1 induced EMT by activation of the PI3K/Akt-GSK-3β-ZEB2 signaling pathway." (PMID 36361979, 2022). "Further, miR-338-3p regulates EMT formation by targeting ZEB2 and MACC1/Met/Akt pathways in gastric cancer." (PMID 34429400, 2021). "In gastric cancer, UCA1 was aberrantly increased and promoted tumor metastasis by significantly induced ZEB2 expression through sponging miR-203." (PMID 33743811, 2021). "IGF-I-induced EMT in gastric cancer cells, accompanied by Zeb2 up-regulation, which involved the Akt/ERK-miR-200c-ZEB2 axis." (PMID 33114139, 2020). "The present study demonstrated that GSK-3β maintained the epithelial phenotype of BGC-823 gastric cancer cells, and PI3K/Akt-GSK-3β signaling is an upstream factor of ZEB2 activation in the IGF-I-induced EMT process." (PMID 25435948, 2015). "The results indicated that IGF-I induced EMT by upregulating ZEB2 expression, which was due to activating the downstream PI3K/Akt signaling pathway in BGC-823 gastric cancer cells." (PMID 25435948, 2015). "Two gastric cancer cell lines were treated with IGF-I to induce EMT and levels of transcription factor ZEB2 and microRNA-200c (miR-200c) were measured." (PMID 24885194, 2014). "We are the first to illustrate a positive regulatory effect of the novel onco‐circRNA circPRELID2 on the translation of ZEB2 mRNA, facilitated by recruiting and mediating RBP O‐GlcNAcylation, highlighting its potential as a therapeutic target in gastric cancer." (PMID 41117067, 2025). "Therefore, β-elemene can reverse EMT in MDR gastric cancer cells by inhibiting the transcription factors ZEB1 and ZEB2 and through the miR-1323/Cbl-b/EGFR pathway." (PMID 34641334, 2021). "In addition, exosomes in gastric cancer downregulate Cbl-b and E-cadherin and upregulate Zincfinger Ebox Binding Homeobox 1 (ZEB-1), ZEB-2, and vimentin in a concentration-dependent manner." (PMID 34641334, 2021). "In addition, exogenous expression of tumor suppressor miR-200c has been found to sensitize gastric cancer cells to trastuzumab by targeting and downregulating ZEB1 and ZEB2." (PMID 32192494, 2020).
gastric cancer (continued). "In addition, ectopic miR-200c has been found to sensitize SGC7901/DDP resistance gastric cancer cells to DDP through inhibiting expression of E-cadherin, Rho family GTPase 3 (RhoE) and ZEB2." (PMID 32192494, 2020). "ZEB2 is an important member of the ZEB family that induces endothelial-mesenchymal transition through repression of E-cadherin and promotes tumor development in gastric carcinoma." (PMID 30923258, 2019). "Consequently, in the present study, the direct role of IGF-I in promoting EMT in gastric cancer and the role of the PI3K/Akt signaling pathway, GSK-3β and ZEB2 in this process was investigated." (PMID 25435948, 2015). "In gastric cancer cells it has been shown that IGF1 is able to induce EMT through the up-regulation of ZEB2, in addition, AKT1/ERK inhibitors revert IGF1-induced EMT through up-regulation of miR-200c, suggesting the involvement of an AKT1/ERK-miR-200c-ZEB2 axis in EMT induced by IGF1 stimulation." (PMID 28880250, 2017). "Therefore, the present study hypothesized that in gastric cancer, downregulation of miR-141 may promote EMT, cancer cell migration, and invasion by targeting the E-cadherin transcriptional repressor ZEB2." (PMID 25975736, 2015). "Gastric cancer patients whose tumors highly expressed ZEB2 or Sp1 had a lower overall survival than those whose tumors did not (n = 631, P = 0.00053 and P = 0.000024 for ZEB2 and Sp1, respectively) when survival within previously published data sets was analyzed using kmPlotter." (PMID 29416649, 2018). "In the present study, it was observed that IGF-I induced EMT and upregulated ZEB2, but not ZEB1, Twist1 or Twist2, in gastric cancer BGC-823 cells." (PMID 25435948, 2015).
lung cancer (53 papers, 2013 to 2025). A malignant neoplasm involving the lung. "Low expression of E-cadherin and high expression of PAX6 and ZEB2 were associated with poor prognosis in lung cancer." (PMID 31024010, 2019). "In lung cancer, down-regulation of miR-218 affects the Slug/ZEB2 signaling pathway and consequentially causes epithelial-mesenchymal transition and metastasis." (PMID 28977866, 2017). "Overexpressed miR-218 in human lung cancer cells increased chemosensitivity to cisplatin therapy through down-regulating ZEB2 and Slug expression." (PMID 37171386, 2023). "To further understand how BATF2 regulates PD-L1, using the TCGA database, we found that lung cancer patients with high BATF2 are negatively correlated with ZEB2 and PI3K signaling pathway." (PMID 37777155, 2023). "Transfection of lung cancer and hepatocellular carcinoma cells with ZEB2 siRNA significantly decreased cancer cell viability in response to Paclitaxel treatment." (PMID 35992812, 2022). "The abrogation of ZEB2 increased paclitaxel sensitivity of lung cancer and hepatocellular carcinoma." (PMID 35992812, 2022). "Hesperidin can promote the apoptosis of lung cancer cells by increasing the expression of miR-132 and reducing the expression of ZEB2, so as to inhibit the proliferation of lung cancer cells." (PMID 36144639, 2022). "LncRNA H19 is also highly expressed in lung cancer, and by inhibiting the function of miR-200a, upregulates the expression of ZEB1 and ZEB2, promoting the epithelial-mesenchymal transition and enhancing lung cancer cell proliferation and metastasis." (PMID 36406130, 2022). "In lung cancer, hesperidin inhibits cell proliferation by targeting the miR-132/ZEB2 signaling pathway." (PMID 36139707, 2022). "miR-132 is reported to restrain the migration and invasion abilities of lung cancer cells by targeting ZEB2." (PMID 34839824, 2021). "Conversely, miR-454-3p was also observed to act as a tumor suppressor in bladder cancer and non–small cell lung cancer by targeting the EMT inducer ZEB2 or constituent Ca2+-binding protein calbindin 1 (CALB1), respectively." (PMID 34017681, 2021). "In lung cancer, miRNA‐145‐5p modulated the epithelial‐mesenchymal transition (EMT) and promoted metastatic infiltration by aiming ZEB2, which controls lung cancer cell migration." (PMID 33527765, 2021). "Formerly, there is also a former study confirmed that FOXM1 cannot affect ZEB2 promoter transcription in lung cancer cells." (PMID 32513952, 2020). "More importantly, our data suggested that elevated expression of miR‐132‐3p, reduced expression of ZEB2, and increased cell proliferation were observed in lung cancer cells treated with DNA methyltransferase inhibitor." (PMID 32500672, 2020). "But no noticeable alteration was found in other transcription factors, including ZEB2, which had been reported to be a direct target of miR-215 in lung cancer and pancreatic cancer." (PMID 30814512, 2019). "In line with ZEB1, TEAD directly transcribes ZEB2 and represses DNp63 to regulate cell fate and lineage conversion in lung cancer progression." (PMID 31212916, 2019). "In conclusion, this study reveals a novel link between the binding of PAX6 to the promoter region of ZEB2 and lung cancer progression." (PMID 31024010, 2019). "To determine if PAX6 can specifically bind the ZEB2 promoter in lung cancer cells, we analyzed binding activity in A549 cells by ChIP assays." (PMID 31024010, 2019). "The down-regulation of miR-218 increases epithelial-mesenchymal transition and tumor metastasis in lung cancer by targeting Slug/ZEB2 signaling." (PMID 28915579, 2017). "However, some studies have shown that ZEB2 can also promote the apoptosis of lung cancer cells and inhibits their proliferation and invasion." (PMID 36969247, 2023). "We confirmed this hypothesis in vitro by using human lung cancer cell lines and found that increasing the expression of BATF2 in lung cancer cells can prevent ZEB2 from entering the nucleus." (PMID 37777155, 2023).